ITGB4 (integrin subunit beta 4)
Diseases named in the same sentence as ITGB4 in open-access papers (continued):
Sharing a sentence is not in itself a finding about the gene and the disease.
ovarian carcinoma (14 papers, 2013 to 2025). A malignant neoplasm originating from the surface ovarian epithelium. "To elucidate the molecular mechanisms underlying the Shh-stimulated ITGB4 response in cellular motility and invasion of ovarian cancer cells, we evaluated FAK protein expression and activation by ITGB4 to determine if they were affected by Hh signaling." (PMID 24533083, 2014). "Importantly, elevated ITGB4 levels were associated with a worse prognosis of R0-resected patients with serous ovarian cancer, supporting a recent study identifying ITGB4 as an independent predictor of adverse progression-free survival in ovarian cancer." (PMID 36932441, 2023). "First, an ovarian cancer patient cohort (n = 252) that contained surgical specimens of primary ovarian cancers was used to study the prognostic role of ITGB4." (PMID 36932441, 2023). "Meanwhile, higher mRNA expression of ITGA3 and ITGB4/8 were significantly associated with poor PFS, lower mRNA expression of ITGA4/A6/A7/A10/AX and ITGB1 were significantly associated with poor PFS in ovarian cancer patients." (PMID 32765584, 2020). "Taken together, these results strongly suggest that the motile and invasive activities of Hh signaling on ovarian cancer cells can be attributed to ITGB4-mediated activation of FAK." (PMID 24533083, 2014). "The Hh signaling pathway induces cell migration and invasion through ITGB4-mediated activation of FAK in ovarian cancer." (PMID 24533083, 2014). "Taken together, these findings demonstrate that Hh signaling modulates the migration and invasion of ovarian cancer cells through ITGB4-mediated activation of FAK signaling." (PMID 24533083, 2014). "Based on these findings, we suggest that the Hh signaling pathway induces metastatic functions of ovarian cancer through ITGB4-mediated activation of FAK." (PMID 24533083, 2014). "To test the possibility of whether ITGB4 mRNA expression levels change in relation to the ovarian cancer cell cycle, we analyzed gene expression profiles across The TCGA ovarian cancer datasets." (PMID 40361400, 2025). "Interestingly, we also found that activation of the Hh signaling pathway in ovarian cancer cells induced ITGB4 gene transcription." (PMID 24533083, 2014). "Our results obtained from human ovarian cancer cell lines SKOV3 cells, which exhibits high invasive behavior, support the Hh signaling promotes cancer cell invasion through integrin β4 (ITGB4)-mediated activation of focal adhesion kinase (FAK) in ovarian cancer." (PMID 24533083, 2014). "Our findings suggest that the diminishment of crosstalk between phosphorylated FAK and ITGB4 due to the down-regulation of Gli family transcription factors might play a pivotal role for the inhibition of ovarian cancer progression." (PMID 24533083, 2014). "Our findings suggest that the diminishment of crosstalk between phosphorylated FAK and ITGB4 due to the down-regulation of Gli family transcription factors might play a pivotal role for inhibiting ovarian cancer progression." (PMID 24533083, 2014). "Furthermore, blockade of ITGB4 signaling by an ITGB4-blocking antibody renders ovarian cancer cells unresponsive to Shh-stimulated migration and invasion, suggesting that the ITGB4 modulates Hh signaling in ovarian cancer migration and invasion." (PMID 24533083, 2014). "Numerous studies have shown that ITGB4-FAK signaling might modulate the metastatic potential of ovarian cancer cells by breaking down basement membrane barriers and promoting cell motility." (PMID 24533083, 2014).
ovarian carcinoma (continued). "Based on previous studies and our data, we speculate that aberrant activation of Hh signaling pathway triggers the cell migration/invasion in ovarian cancer cells via ITGB4-mediated FAK signaling." (PMID 24533083, 2014). "In an intraperitoneal (i.p.)carcinomatosis xenograft model, in which human ovarian cancer cells (SKOV3) were i.p. injected into SCID mice, the same synergism of ITGB4 KD and E-/P-selectin KO could be observed." (PMID 36932441, 2023). "In ovarian cancer, the Hh signaling pathway could induce cell migration and invasion through the activation of FAK, which was mediated by ITGB4." (PMID 34402716, 2021). "Hence, we surmised a critical role of alpha3beta4 heterodimer or distinctly independent functions of ITGB4 and ITGA3 played in ovarian cancer." (PMID 32765584, 2020). "However, the database analysis revealed that YKL40 and ITGB4 expression was higher in ovarian cancer tissues than in normal tissues and that PFS was poorer in the groups with high-level expression of YKL40 and ITGB4." (PMID 39408927, 2024). "However, to date, no evaluations of ITGB4 immunostaining in ovarian cancer have been reported." (PMID 39408927, 2024). "We found that Shh stimulation of ovarian cancer cells induced phosphorylation of FAK (Tyr397), but not expression of FAK, whereas treatment with GANT61 or an ITGB4-blocking antibody resulted in a significant decrease in phosphorylation of FAK (Tyr397)." (PMID 24533083, 2014). "For example, in ovarian cancer cells, Spectrin beta non-erythrocytic 2 (SPTBN2) may promote tumor migration and invasion by inhibiting the expression of focal adhesion-related proteins and downstream signaling pathways via ITGB4." (PMID 39169946, 2024).
colon cancer (11 papers, 2013 to 2024). "Further, Kaplan-Meier curves and univariate analysis demonstrated high ITGB4 expression was significantly associated with unfavorable overall survival in colon cancer (HR=1.292, 95%CI=1.084-1.540, P=0.004)." (PMID 31602273, 2019). "When evaluating the association of ITGB4 with clinical features and MSI status in colon cancer, we found that high ITGB4 expression was associated with elder onset age, proximal tumor location, and MSH status." (PMID 31602273, 2019). "In conclusion, ITGB4 is highly expressed in human colon cancer and associated with poor overall survival." (PMID 31602273, 2019). "Then all the datasets were integrated and high ITGB4 expression was found to be significantly associated with unfavorable overall survival in colon cancer (HR=1.574, 95%CI=1.305-1.900, P<0.001)." (PMID 31602273, 2019). "Another study in TNBC shows that secretion of ITGB4 from cancer cells via exosomes triggers glycolysis in cancer-associated fibroblasts and the gene has also been reported as a novel prognostic factor in colon cancer." (PMID 38447798, 2024). "However, the reports on the associations of ITGB4 with clinicopathological features and/or outcomes in colon cancer are rare." (PMID 31602273, 2019). "ITGB4 was also reported to induce tumorigenesis of colon cancer though activating focal adhesion signalling pathway." (PMID 33073486, 2020). "In the present study, we utilized the large public datasets from NCBI GEO and TCGA databases and collected clinical samples in our center to investigate the expressions of ITGB4 at transcriptional level and explore its clinical significance in colon cancer." (PMID 31602273, 2019). "FOSL1 was also found to be highly expressed in colon cancer tissues as well as ITGB4 in TCGA-colon cancer cohort." (PMID 31602273, 2019). "The statistical analyses suggested that ITGB4 mRNA expressions were up-regulated significantly in colon cancer." (PMID 31602273, 2019). "The AS of CALD1, COL6A3, FN1, MAST2, LGR5 and ITGB4 were previously validated in colon cancer using RT-PCR24, while CLSTN1, AUP1, CTNND1, CALD1 and COL6A3 were shown to exhibit tumour-specific splice variants in colon, bladder and prostate cancers." (PMID 28592875, 2017). "A recent study indicated that ITGB4 might be a prognosis marker for the individual therapy of colon cancer." (PMID 34361106, 2021). "Our results revealed that ITGB4 might be a therapeutic target and prognosis marker for individual therapy of colon cancer." (PMID 31602273, 2019). "In addition, ITGB4 co-expressed genes were annotated to investigate how ITGB4 promoted colon cancer development." (PMID 31602273, 2019). "In our study, we did not assess the association of ITGB4 expression with colon cancer differentiation due to the lack of related clinical information." (PMID 31602273, 2019). "We found that high ITGB4 expression was associated with elder onset age, proximal tumor location, and MSH status in GSE39582, with M stage in GSE41258, and with MSH status in TCGA colon cancer dataset." (PMID 31602273, 2019). "In addition, we determined the methylation of ITGB4 promoter and found methylation of ITGB4 promoter was negatively correlated with ITGB4 expression and down-regulated in colon cancer." (PMID 31602273, 2019). "The elevated ITGB4 transcription in colon cancer might due to its upstream transcription factor FOSL1 up-regulation and its promoter hypomethylation." (PMID 31602273, 2019). "Currently, little was known on the molecular mechanism of ITGB4 in colon cancer." (PMID 31602273, 2019). "The molecular regulation mechanism of ITGB4 ectopic expression in colon cancer was also explored and the results indicated that ITGB4 might be up-regulated by the transcription factor FOSL1 (FOS like 1, AP-1 Transcription Factor Subunit) and its promoter hypomethylation." (PMID 31602273, 2019).
colon cancer (continued). "The annotation of ITGB4 co-expressed genes suggested the pathways including cell growth, positive regulation of cell migration, and apoptotic signaling might be involved in the potential mechanisms of ITGB4 in colon cancer development." (PMID 31602273, 2019). "ITGB4 might be a therapeutic target and prognosis marker for individual therapy of colon cancer." (PMID 31602273, 2019). "Importantly, we found that high ITGB4 expression was significantly associated with unfavorable overall survival in colon cancer (HR=1.574, 95%CI=1.305-1.900, P<0.001), which has not been reported previously." (PMID 31602273, 2019). "Unpaired and paired Mann Whitney U test and ANOVA were performed to compare the expressions of ITGB4 in colon cancer tissues with adjacent non-tumor tissues or tissues from healthy subjects." (PMID 31602273, 2019). "The statistical analyses suggested that ITGB4 mRNA expressions were up-regulated significantly in colon cancer compared with adjacent controls in GSE39582, GSE44076, and TCGA-colon cancer, and with healthy controls in GSE44076." (PMID 31602273, 2019). "Potential regulation mechanisms of ITGB4 aberrant expression in colon cancer were also not very clear." (PMID 31602273, 2019). "Currently, ITGB4 has been characterized in colon cancer, however, its clinical significance is not very clear." (PMID 31602273, 2019). "In addition, we collected tumor tissues and corresponding adjacent non-tumor tissues from 65 patients with colon cancer and analyzed the ITGB4 expression with qRT-PCR and also found that ITGB4 expression in tumor tissues was higher than adjacent tissues." (PMID 31602273, 2019). "Whereas, we found that ITGB4 ectopic expression might be regulated by the up-regulation of the transcription factor FOSL1, the down-regulation of miR-335-5p, and its promoter hypomethylation in colon cancer." (PMID 31602273, 2019).
gastric cancer (10 papers, 2015 to 2024). A primary or metastatic malignant neoplasm involving the stomach. "Among them, ITGB4, located at 17q25.1, has been reported to be aberrantly expressed in several cancers, including breast, pancreatic, lung, and gastric cancers, and may be positively associated with poor prognosis." (PMID 34414684, 2021). "ECM1 promotes tumor metastasis through epithelial–mesenchymal transition (EMT) progression, L Gan demonstrated ECM1 induced SOX2 expression via direct interaction with integrin β4 (ITGB4) in gastric cancer and thus altering gene expression of EMT factors." (PMID 31335317, 2019). "ITGB4-mediated invasion and migration of gastric cancer cells is also regulated by metallopanstimulin-1." (PMID 30361615, 2019). "Recently, Transmembrane protein 268 (TMEM268) was reported to increase ITGB4 expression via enhancing its stability in gastric cancer cells." (PMID 30658712, 2019). "Increasing evidence indicates that the overexpression of ITGB4 is correlated with an aggressive phenotype and poor prognosis in breast cancer, lung cancer, pancreatic cancer, cervical cancer, and gastric cancer." (PMID 30361615, 2019). "Similarly, in gastric cancer, MPS-1 plays a regulatory role in invasion and migration by influencing ITGB4 expression." (PMID 39169946, 2024).
epidermolysis bullosa (9 papers, 2015 to 2025). Epidermolysis bullosa (EB) is a group of genetic skin diseases that cause the skin to blister very easily. "ITGB4 (OMIM: #147557) is associated with epidermolysis bullosa with autosomal dominant inheritance." (PMID 37895187, 2023). "Furthermore, the identification of the ITGB4 mutation means that affected sheep can be used as a large mammal animal model for the human form of epidermolysis bullosa with aplasia cutis." (PMID 25955497, 2015). "Notably, LAMA3, LAMB3, and ITGB4 are involved in junctional epidermolysis bullosa." (PMID 37745851, 2023).
asthma (8 papers, 2012 to 2023). "Although the association between ITGB4 and asthma has been verified, little is known about the contribution of ITGB4 to mucus hypersecretion after RSV infection in childhood asthma." (PMID 34975337, 2022). "ITGB4 is a down-regulated structural adhesion molecule in the airway epithelia of asthma patients which is strongly associated with asthma susceptibility." (PMID 35958591, 2022). "Of note, integrin β4 (ITGB4) is down-regulated in the airway epithelia of asthma patients which is implicated in asthma susceptibility." (PMID 35958591, 2022). "Our previous study found that integrin β4 (ITGB4) is decreased in the airway epithelium of asthma patients with specific variant site." (PMID 31970850, 2020). "Combined with previous experimental results that ITGB4−/− mice presented BD-like behavior in our study, these findings verified that Th2 inflammation played a critical role in the association between asthma and BD in ITGB4−/− mice." (PMID 30170608, 2018). "The ITGB4-deficient mice provide a validated animal model for us to study the possible mechanism of BD-like psychiatric comorbidity of asthma patients." (PMID 30170608, 2018). "Foregoing results suggest that the deficiency of ITGB4 could be relevant to asthma susceptibility." (PMID 37698050, 2023). "Besides, ITGB4 deficiency could also result in severe airway inflammation and airway hyperresponsiveness in asthma." (PMID 32117985, 2020). "And ITGB4 deficiency may play an important role in airway inflammation of asthma patients." (PMID 30170608, 2018). "Our previous studies have found that the expression of integrin β4 (ITGB4) is downregulated in asthma patients." (PMID 37698050, 2023). "Our group found that integrin β4 (ITGB4) is downregulated in the airway epithelium of asthma patients." (PMID 37698050, 2023). "Based on the foresaid facts, we speculated that the expression defect of ITGB4 may affect fetal lung development and has a continuous effect till adolescence or even adulthood, thereby increasing the susceptibility of chronic respiratory system diseases such as asthma." (PMID 37698050, 2023). "Integrin β4 (ITGB4) is down-regulated in the airway epithelial cells (AECs) of asthma patients which plays a critical role in the pathogenesis of asthma." (PMID 34975337, 2022). "Of note, expression of ITGB4 decreased significantly by specific variation sites in the AECs of asthma patients." (PMID 34975337, 2022). "Our previous work found that ITGB4, a structural adhesion molecule, is downregulated in airway epithelial cells of asthma patients with four variation sites in 5′ flanking region." (PMID 30170608, 2018). "Our results suggested that ITGB4 knockout induced chronic inflammation mediated the comorbidity of asthma and BD." (PMID 30170608, 2018). "Our previous work demonstrated that structural adhesion molecule integrin β4 (ITGB4) is downregulated in asthma airway epithelial cells." (PMID 22545078, 2012). "The regulation of antigen presentation after ITGB4 silencing would have a close relationship to the asthma airway inflammation." (PMID 22545078, 2012). "Accumulating evidence shows that ITGB4, SEMA3D, FCAR (Fc fragment of IgA receptor), KIT (KIT proto-oncogene, receptor tyrosine kinase), PGLYRP1, IL17RB, BIRC5 and PTGS1 are associated with prognosis in asthma." (PMID 36837510, 2023). "However, little is known about the influence of ITGB4 deficiency on RSV infection and subsequent asthma susceptibility." (PMID 35958591, 2022). "ITGB4 is a down-regulated adhesion molecular in the airway epithelia of asthma patients which may participate in the regulation of RSV infection related intracellular pathways." (PMID 35958591, 2022). "Therefore, we thought to further explored the influence of ITGB4 deficiency on RSV-infected airway epithelia and subsequent asthma susceptibility." (PMID 35958591, 2022).
asthma (continued). "ITGB4 deficiency in adult mice aggravated the lung Th2 immune responses and enhanced airway hyper‐responsiveness (AHR) with a house dust mite (HDM)‐induced asthma model." (PMID 31970850, 2020). "Integrin β4 (ITGB4) is downregulated on the airway epithelial of asthma patients, which might play a critical role in the parthenogenesis of airway inflammation." (PMID 30170608, 2018). "Thus, our results verified the influence of Th2 inflammation induction by ITGB4 low expression on asthma airway epithelial cells." (PMID 22545078, 2012). "In addition, silencing of ITGB4 in asthma airway epithelial cells led to impaired antigen presentation." (PMID 22545078, 2012). "Our previous study demonstrated that ITGB4 is downregulated in asthma airway epithelial cells, which may result in decreased wound repair and anti-oxidation ability." (PMID 22545078, 2012). "Thus, epithelial cell senescence induced by the downregulation of ITGB4 or increased TSLP leading to airway epithelium dysfunction, might be an important mechanism of asthma pathogenesis." (PMID 32117985, 2020).